TRPV4 (transient receptor potential cation channel subfamily V member 4)
Diseases named in the same sentence as TRPV4 in open-access papers (continued):
Sharing a sentence is not in itself a finding about the gene and the disease.
neuropathy (continued). "These phenotypes are prevented by TRPV4 antagonists, which hold promise as a therapeutic strategy for the treatment of patients with TRPV4-associated neuropathies." (PMID 32471994, 2020). "Minor skeletal abnormalities in association with a neuropathy were reported in some patients with TRPV4 mutations previously." (PMID 25900305, 2015). "The findings of the present study showing insulin-induced TRPV4 channel sensitization may provide further insights into the mechanisms underlying acute insulin treatment-induced neuropathy after intensive glycemic control." (PMID 40343778, 2025). "These insights give us a hint that TRPV4-mediated mechanisms implicated in neuropathy such as CMT and Alzheimer’s, where mitochondrial dysfunction is pivotal, could contribute to neuronal degeneration and dysfunction." (PMID 39333347, 2025). "In cases involving neuropathy-causing TRPV4 mutants, the potential reduction in interaction between RhoA and TRPV4 could potentially influence RhoA involved migration process." (PMID 39333347, 2025). "On the other hand, TRPV4 appears to be upregulated in a variety of pathological conditions, being associated with inflammatory diseases affecting the central and peripheral nervous system, such as osteoarthritis, atherosclerosis, cancer pain, and neuropathies." (PMID 38730655, 2024). "We previously showed that the cytoskeleton remodeling small GTPase RhoA interacts with TRPV435, but this interaction appears to be perturbed by neuropathy mutations resulting in increased TRPV4 channel activity, cytoskeletal remodeling, and cell process retraction." (PMID 37353484, 2023). "Notably, while skeletal dysplasia mutations are distributed throughout the TRPV4 channel, neuromuscular disease-causing mutations (referred to hereafter as neuropathy mutations) are primarily localized to a confined region of the N-terminal cytoplasmic domain." (PMID 37353484, 2023). "Together, these data further highlight the importance of N-terminal IDR ubiquitination in modulating TRPV4 channel activity and identify alterations of this pathway resulting from neuropathy-causing mutations that can be partially rescued by enhancing TRPV4 ubiquitination." (PMID 35300980, 2022). "In addition, a fly model of neuropathy observed that mutations within the TRPV4 cause disruption of axonal interactions and dendritic degeneration." (PMID 36670886, 2022). "A puzzling feature of TRPV4-related disease is the tissue specificity associated with human mutations despite similar gain of ion channel function with expression of both skeletal dysplasia and neuropathy mutants in heterologous systems." (PMID 33664271, 2021). "Finally, the inhibitory effect of RhoA on WT TRPV4 ion channel activity is abolished by TRPV4 neuropathy-causing mutations." (PMID 33664271, 2021). "Studies of TRPV4 disease mutants in heterologous systems have demonstrated that both neuropathy and skeletal dysplasia mutations lead to gain of ion channel function, increased basal and stimulated TRPV4-mediated calcium influx, and cytotoxicity that can be rescued with channel antagonists." (PMID 33664271, 2021). "Together these results identify RhoA as a critical mediator of TRPV4-induced cell structure changes and suggest that disruption of TRPV4-RhoA binding may contribute to tissue-specific toxicity of TRPV4 neuropathy mutations." (PMID 33664271, 2021). "The clustering of neuropathy mutations within the TRPV4 ARD suggests that these mutations may specifically disrupt scaffolding functions of TRPV4." (PMID 33664271, 2021). "Given that the majority of neuropathy-causing mutations in TRPV4 cluster within the exposed face of the intracellular ARD that mediates protein–protein interactions, we tested whether neuropathy mutations specifically alter TRPV4–RhoA interaction." (PMID 33664271, 2021).
neuropathy (continued). "Together, our results uncover a complex interplay between TRPV4 and RhoA in regulating cell morphology and suggest that increased RhoA activation may be an important pathologic consequence of TRPV4 neuropathy mutations." (PMID 33664271, 2021). "Together, our results demonstrate that neuropathy mutations within the TRPV4 ARD specifically disrupt the ion channel-independent scaffolding function of TRPV4, which may be an important pathological event contributing to neuron-specific disease." (PMID 33664271, 2021). "Interrogation of the cellular events underlying TRPV4-associated neuropathy may provide insights into mechanistic links between Ca2+ and impaired axonal transport in neurodegenerative disease." (PMID 32471994, 2020). "Therefore, dysregulation of autophagy is a potential pathomechanism in TRPV4 associated neuropathies, as a direct effect of mutant TRPV4 or as one of the neurotoxic consequences due to the disruption in calcium concentrations by TRPV4 mutants." (PMID 28553203, 2017). "Mutations in the TRPV4 gene have a broad phenotypic variability and disease severity and may share a similar pathogenic mechanism with Heat Shock Protein related neuropathies." (PMID 25900305, 2015). "While the localization of neuropathy-associated TRPV4 mutations at the TRPV4-RhoA interface suggests that control of this signaling complex is particularly important in the nervous system, TRPV4-RhoA interactions are likely to play a fundamental role in signaling in other disease states as well." (PMID 37353484, 2023). "The pathogenic mechanisms underlying TRPV4 neuropathy and skeletal dysplasia remain unknown." (PMID 33664271, 2021). "Furthermore, small molecule inhibition of TRPV4 ameliorates TRPV4-mediated phentoypes in Drosophila, suggesting that TRPV4 antagonism is a promising therapeutic strategy for the treatment of patients with TRPV4-associated neuropathies." (PMID 32471994, 2020). "In the nervous system, elevated intracellular Ca2+ by TRPV4 through Ca2+/CaMKII-mediated mechanisms disrupted mitochondrial transportation, leading to axonal degeneration in neuropathy." (PMID 41555550, 2026). "Previous studies have also shown that these PTMs contribute to dysregulation of the TRPV4 channel and thereby lead to various diseases like skeletal dysplasia, neuropathies, and cardiovascular diseases." (PMID 41555550, 2026). "This is especially complicated when considering TRPV4-related neuropathy and skeletal dysplasia show high variations between affected individuals even within the same family." (PMID 39333347, 2025). "However, it remains an enigma whether all identified neuropathy-causing mutants exhibit similar decreased TRPV4-Rho interaction pattern, and if proven true, this finding would substantially enhance our comprehension of the molecular mechanisms underlying TRPV4-related peripheral neuropathy." (PMID 39333347, 2025). "Recent research has also demonstrated that the in vivo expression of a neuropathy-inducing TRPV4 mutant (TRPV4R269C) leads to neuronal dysfunction and axonal degeneration." (PMID 39333347, 2025). "In terms of morphological effects, neuropathy mutants of TRPV4 harboring neuronal cell line display impaired neurite length growth compared to transfected wild-type TRPV4 in MN-1 cells." (PMID 39333347, 2025). "A third research group aimed to study the simultaneous expression of extracellular-signal-regulated kinase (ERK1/2) and TRPV4 to obtain an indication of tumor progression in a cancer-induced neuropathy model." (PMID 38730655, 2024). "Altogether, this case broadened the phenotype spectrum and provided the nerve biopsy pathological details of TRPV4-related neuropathies." (PMID 37391745, 2023). "Consistent with our structure, previous studies showed that neuropathy-related mutants R232C, R237L, R269C, and R315W disrupt protein-protein interactions between TRPV4 and RhoA13." (PMID 37353478, 2023).
neuropathy (continued). "Restoring ubiquitination of neuropathy mutant TRPV4 through expression of NEDD4 was able to ameliorate increased channel activity." (PMID 35300980, 2022). "In a Drosophila model of TRPV4 neuropathy, we also observed reduced ubiquitination of R269C TRPV4 as well as rescue of TRPV4 Ub levels in flies expressing R269C TRPV4 along with the pore-inactivating M680K mutation." (PMID 35300980, 2022). "PGC1A is also negatively regulated by TRPV4, while TRPV4 antagonists reduce high‐fat diet‐induced obesity, insulin resistance, diabetic nephropathy, retinopathy, and neuropathy." (PMID 39086962, 2022). "Research into the involvement of Trpv4 in neuropathies and neurodegenerative diseases has attracted an increasing interest." (PMID 35022531, 2022). "These performances reinforced the notion that clinical features are heterogeneous in TRPV4-related neuropathies and skeletal dysplasia." (PMID 36118854, 2022). "We also generated recombinant TRPV4 ARD WT (hV4-ARD-WT), TRPV4 ARD R269C neuropathy mutant (hV4-ARD-R269C), and full-length RhoA." (PMID 33664271, 2021). "We first tagged WT and neuropathy mutant TRPV4 with different epitope tags and used co-immunoprecipitation to confirm that WT and mutant TRPV4 were able to associate in cells." (PMID 33664271, 2021). "Our work elucidates several important consequences of the failure of TRPV4–RhoA interaction in neuropathy mutants." (PMID 33664271, 2021). "We also generated a stable HEK293T cell line that inducibly expresses FLAG-tagged WT or R269C neuropathy mutant TRPV4 in response to tetracycline treatment." (PMID 33664271, 2021). "Underscoring the pathological importance of increased RhoA activity, we find that TRPV4 neuropathy mutant-induced axonal and dendritic degeneration can be rescued in vivo by genetic inhibition of the Drosophila RhoA ortholog Rho1." (PMID 33664271, 2021). "We also utilized the T-Rex-TRPV4 cells to demonstrate that the neuropathy mutant R269C disrupts interaction with endogenous RhoA." (PMID 33664271, 2021). "We next performed co-immunoprecipitation with over-expressed RhoA and FLAG-tagged WT TRPV4 alone or in combination with GFP-tagged WT or neuropathy mutant TRPV4." (PMID 33664271, 2021). "Given the abnormalities of MN-1 neurite outgrowth with expression of neuropathy mutant TRPV4, we were particularly interested in examining the impact of RhoA on sensory neuron morphology and degeneration in the fly model." (PMID 33664271, 2021). "Strikingly, we found that genetic inhibition of the activity of the Drosophila RhoA ortholog Rho1 by expression of dominant negative Rho1[T19N] rescued both dendritic and axonal degeneration with expression of neuropathy mutant TRPV4." (PMID 33664271, 2021). "In animal models of chemotherapy-induced neuropathy, in which mitochondrial trafficking defects are well-established, inhibition of TRPV4 activity is partially protective." (PMID 32471994, 2020). "This complex forms the foundation of TRPV4-related diseases and may shed light on TRPV4’s involvement in various conditions, including neuropathy." (PMID 39333347, 2025). "Furthermore, inhibition of RhoA restores neurite length in vitro and in a fly model of TRPV4 neuropathy, as demonstrated in a fly model of TRPV4 R269C mutant, which mimics TRPV4 neuropathy." (PMID 39333347, 2025). "Even though the inhibitory neurite growth can explain the mechanism of TRPV4-related neuropathy, it is essential to recognize that other mechanisms may also contribute to TRPV4-related neuropathy." (PMID 39333347, 2025). "Moreover, the TRPV4-selective antagonist (HC-067047) was presented as a successful drug for the treatment or relapse of several neuropathies." (PMID 38730655, 2024). "With expression of TRPV4 mutants that fail to interact with RhoA (TRPV4 E183A/C/K or D263A/L/K/N), we found increased basal and hypotonic saline-induced calcium influxes, similar to the neuropathy mutant R269C35." (PMID 37353484, 2023).
neuropathy (continued). "Having observed that increasing WT TRPV4 ubiquitination reduces stimulated calcium responses, we postulated that increasing the ubiquitination of neuropathy mutant TRPV4 might ameliorate its gain-of-channel function." (PMID 35300980, 2022). "In this context, it is interesting to note that neither a gain- nor a loss-of-function of TRPV4 causes skin disease, although pathologies of skeletal growth and neuropathy are observed." (PMID 35098357, 2022). "Therefore, TRPV4 contributes to enhanced nociception in the paclitaxel-induced neuropathy model in rats by activating primary afferent nociceptors depending on the integrin/Src kinase pathway." (PMID 36670886, 2022). "We show that TRPV4–RhoA interactions are markedly disrupted by neuropathy-causing mutations within the TRPV4 N-terminal ARD, but not by skeletal dysplasia mutations on the opposing face of the ARD." (PMID 33664271, 2021). "Neuropathy but not skeletal dysplasia mutations disrupt TRPV4-RhoA binding and cytoskeletal outgrowth." (PMID 33664271, 2021). "However, inhibition of RhoA restores neurite length in vitro and in a fly model of TRPV4 neuropathy." (PMID 33664271, 2021). "Importantly, we also show that co-expression of neuropathy mutant TRPV4 with WT TRPV4 has an inhibitory effect on the interaction of WT TRPV4 with RhoA." (PMID 33664271, 2021). "Given that TRPV4 mutations cause axonal neuropathy, TRPV4–RhoA interactions may have a direct impact on neuronal development or maintenance, as suggested by our results in a fly model of TRPV4 neuropathy." (PMID 33664271, 2021). "Besides the general features of TRPV4 neuropathies, this condition is characterized by a reduction in shoulder blade muscles causing the typical appearance of “scapular winging”." (PMID 33467654, 2021). "Remarkably, neuropathy mutations, but not skeletal dysplasia mutations, disrupt TRPV4–RhoA interactions and TRPV4-mediated regulation of cellular outgrowth." (PMID 33664271, 2021). "Based on these collective results, we hypothesized that over-activation of RhoA might contribute to the pathogenesis of TRPV4 neuropathy, and that inhibition of RhoA could potentially rescue mutant TRPV4-mediated neuronal degeneration." (PMID 33664271, 2021). "However, RhoA FRET was significantly greater with agonist stimulation of neuropathy mutant TRPV4, with more rapid onset, longer duration, and higher peak RhoA activation." (PMID 33664271, 2021). "Here, we show that in vivo expression of a neuropathy-causing TRPV4 mutant (TRPV4R269C) causes dose-dependent neuronal dysfunction and axonal degeneration, which are rescued by genetic or pharmacological blockade of TRPV4 channel activity." (PMID 32471994, 2020). "Hearing loss could develop simultaneously with neuropathy, in some patients with pathogenic variants in PRPS1 (n = 1), NEFL (n = 2), MPZ (n = 1), TRPV4 (n = 1); or at a distance in some cases of variants in SH3TC2 (n = 2) and ABHD12 (n = 1)." (PMID 31393079, 2019). "Vocal cord paralysis and, to a lesser extent, neurosensory deafness are described as clinical clues to diagnose TRPV4 associated neuropathies; however none of these were present in our patients." (PMID 25900305, 2015). "We speculate that TRPV4 mutations are associated with the production of misfolded proteins, which can form cytoplasmic aggregates similar to HSP related neuropathies." (PMID 25900305, 2015). "While current studies do not directly link mutated mitochondrial TRPV4 with neuropathy, understanding TRPV4’s impact on mitochondrial function offers new insights into the development of neurological disorders characterized by mitochondrial dysfunction affecting neurite extension." (PMID 39333347, 2025). "Here, we demonstrate that reduced ubiquitination of neuropathy-causing TRPV4 mutants is not a result of an intrinsic defect in their ability to be ubiquitinated, but is rather a consequence of the gain-of-ion channel function and resultant increased intracellular calcium levels." (PMID 35300980, 2022).
neuropathy (continued). "Thus, uncoupling of neuropathy mutant TRPV4 from its normal binding partners and regulatory functions may contribute to the neuronal specificity in TRPV4-mediated neuropathy." (PMID 33664271, 2021). "We next addressed whether RhoA could suppress calcium influx via neuropathy mutant TRPV4." (PMID 33664271, 2021). "Further investigation of functional interactions between TRPV4 and mitochondrial biology will help elucidate the precise contributions of these potential pathological mechanisms and could refine therapeutic strategies for a range of neuropathies." (PMID 32471994, 2020). "No studies have yet examined the effects of neuropathy-causing TRPV4 mutations on neurons in vivo." (PMID 32471994, 2020). "On day 3 after cancer cells’ injection, TRPV4 and ERK1/2 positive immunoreactive (+IR) neurons were overexpressed, with subsequent downregulation from day 7 until day 14 after cancer-induced neuropathy." (PMID 38730655, 2024). "In rodent models of T2DM, TRPV4 agonists promote vasodilation and improve cardiovascular function, whereas TRPV4 antagonists reduce HFD-induced obesity, insulin resistance, DN, retinopathy and neuropathy (Ref." (PMID 38659380, 2024). "In this cancer-neuropathy model, the inhibition of TRPV1 and TRPV4 channel activity by their selective antagonists, capsazepine and HC-067047, respectively, transiently reversed the cancer-induced thermal and mechanical allodynia in a dose-dependent manner." (PMID 38730655, 2024). "Blocking Ca2+ influx through TRPV4 channels with the TRPV4 inhibitor HC067047 reduces the death of cultured dorsal root ganglion neurons and alleviates paclitaxel-induced neuropathy." (PMID 30455633, 2018). "Expression of WT TRPV4 attenuated colchicine-induced RhoA activation, whereas neuropathy mutant TRPV4 failed to exert an effect on RhoA activation in response to colchicine." (PMID 33664271, 2021). "Given our finding that WT but not neuropathy mutant TRPV4 interacts with RhoA, we next sought to determine the functional consequences of this interaction for RhoA function." (PMID 33664271, 2021). "Both TRPV4 and TRPV1 have been suggested to contribute to paclitaxel-induced neuropathy." (PMID 33105614, 2020). "A few muscle pathology descriptions in TRPV4-related neuropathies point towards a chronic neurogenic process without any specific or distinguishable features." (PMID 25900305, 2015). "TRPV4, among the various TRP channels, was initially discovered in the kidneys of rats and identified as a vertebrate homolog of the Caenorhabditis elegans gene Osm-9, emerges as a key player in numerous pathological processes, including neuropathy, skeletal dysplasia, tumors, and inflammation." (PMID 39333347, 2025). "However, in diabetic patients with neuropathy, the TRPV4 expression did not change in the skin nerve fibers." (PMID 36670886, 2022). "We demonstrate direct interaction of the TRPV4 ARD with inactive, GDP-bound RhoA, and further show how mutual TRPV4–RhoA inhibition and TRPV4 calcium-dependent activation of RhoA play important roles in modulating cellular outgrowth, both in cultured cells and in a fly model of TRPV4 neuropathy." (PMID 33664271, 2021). "In contrast, neuropathy mutant TRPV4 did not inhibit basal RhoA activation (compare lanes 1 and 2 of T-Rex-TRPV4R269C blot), consistent with a requirement for binding of TRPV4 and RhoA for inhibition of RhoA activation." (PMID 33664271, 2021). "Neuropathy mutant TRPV4 failed to promote neurite growth, and this effect could not be rescued by ion channel inhibition with HC067, suggesting an ion channel-independent disruption of cytoskeletal modulation in neuropathy mutants." (PMID 33664271, 2021).